RN7SKP285 (RN7SK pseudogene 285)
Gene: Miscellaneous RNA gene on chromosome 1 (103,523,562 to 103,523,879, forward strand). Ensembl gene ENSG00000222069.
Homologues: Orthologues: chimpanzee 7SK (89% identical). Paralogues in human: 7SK (66% identical), RN7SKP124 (66% identical), RN7SKP180 (64% identical), RN7SKP77 (64% identical), RN7SKP176 (64% identical), RN7SKP62 (64% identical), RN7SKP78 (64% identical), RN7SKP203 (63% identical), RN7SKP79 (63% identical), RN7SKP71 (63% identical), RN7SKP20 (63% identical), RN7SKP8 (63% identical), and 284 more.